TLR7 (toll like receptor 7)
Diseases named in the same sentence as TLR7 in open-access papers (continued):
Sharing a sentence is not in itself a finding about the gene and the disease.
infection (continued). "The loss of TLR7 also correlated with a dramatic reduction of the germinal center response to infection, indicating that TLR7 activation drives the formation or maintenance of germinal centers during retroviral infection." (PMID 33202596, 2020). "We analyzed the expression levels of anti-viral molecules associated with TLR7 downstream signaling as well as proinflammatory cytokines in the spinal cord by quantitative PCR at day 3 and 6 post-infection." (PMID 33679702, 2020). "Double TLR7/9 deficiency resulted in additive lethality, with 62% of the doubly deficient animals succumbing to infection between 4 and 6 days after challenge." (PMID 32209688, 2020). "Infection with influenza viruses caused a significant reduction in the expression of TLR-7 and MDA5 in MK1-OSU cells and TLR-7 in SD-PJEC cells at the protein level." (PMID 29880757, 2018). "This is in accordance with animal models of infection, which found that naive myd88−/−tlr3−/− and tlr7−/− mice were more susceptible to influenza virus infection, demonstrating that MyD88 signaling is important in resisting primary challenge." (PMID 29552008, 2018). "To better understand the mechanisms at play in the protective action of Tlr7-deficiency, we next performed a microarray analysis of BMMs 24 h after infection with S. Typhimurium." (PMID 29616197, 2018). "Another study demonstrated that both duck and chicken TLR7 are only transiently expressed in PBMCs at the early stages of low pathogenic avian influenza virus H11N9 infection, followed by a decline as the infection progresses." (PMID 25874762, 2015). "We assessed the effect of triggering TLR2, TLR3, TLR4, and TLR7 with selected ligands on the susceptibility of the J774A.1 macrophage cell line to infection with murine coronavirus (mouse hepatitis virus, [MHV])." (PMID 22754655, 2012). "TLR7-deficient mice fail to develop a potent serum antibody response after infection with FV, and this correlates with a significant reduction in the formation of GL7+ germinal center B cells." (PMID 21998589, 2011). "Using wild-type and TLR7-deficient mice, we show that TLR7 activation enhances early antiviral T cell responses but subsequently increases PD-L1/PD-L2 expression, promoting T cell exhaustion at later stages of infection." (PMID 41704774, 2026). "TLR7, located on the X chromosome and capable of escaping X inactivation, is expressed at higher levels in women, enhancing immune response and reducing susceptibility to infections compared to men." (PMID 41516251, 2025). "This hypothesis is further supported by our observation that TLR7 KO mice exhibited less body weight loss during infection, suggesting a less severe disease course compared to WT mice." (PMID 40442368, 2025). "Furthermore, characterising the dissemination of inflammation from the URT to LRT following infection with more pathogenic strains of IAV will provide important insights into the broad role of TLR7." (PMID 40442368, 2025). "Next, to elucidate whether TLR7 deficiency results in differential infection and tissue distribution of the virus, we performed an immunohistochemical examination of the SARS-CoV-2-N antigen in infected control and TLR7-deficient lungs." (PMID 40162785, 2025). "Although the polymorphisms did not influence the presence of symptoms of diseases caused by HTLV-1, carriers of the wild-type alleles for TLR7 rs179008 (A/T) and the polymorphism for TLR7 rs3853839 (C/G) appears to have a stronger antiviral response and increased infection control." (PMID 39650644, 2024). "Moreover, TLR7 has also been implicated in regulating eosinophil-driven allergic airway inflammation following infection with other RNA viruses such as rhinovirus or Sendai virus." (PMID 39769461, 2024). "This shift to Th2 dominance might have contributed to the IAV-induced lung dysfunction in TLR7-deficient mice after the acute phase of the infection." (PMID 39769461, 2024).
infection (continued). "TLR7 is also implicated in other infection diseases, such as Pseudomonas aeruginosa pneumonia or Helicobacter pylori infection, and TLR7 or TLR7/8 antagonist might play a positive role in bacterial recognition and treatment." (PMID 36677692, 2023). "A few examples of immune related genes that, during the persistent Bb infection, were down-regulated in P. leucopus mice and remained unresponsive in C3H mice include TLR7-encoding gene, type I IFN-associated genes, and members of the lymphocyte antigen-6 (Ly6) gene family." (PMID 37113133, 2023). "Moreover, in 4 male subjects with severe forms of COVID‐19, loss of function variants of X‐chromosomal TLR7 were identified infection that resulted in a deficiency in the responses by type 1 and 2 IFNs." (PMID 35538443, 2022). "Notably, during infection of TLR7-deficient mice, plasma cytokines were elevated for most inflammatory cytokines but attenuated for IL-10, indicating the existence of a TLR7-independent pathway promoting inflammatory cytokine secretion." (PMID 33202596, 2020). "Accordingly, we hypothesized that TLR7 deficiency in skin DC resulted in inefficient transport of the skin-borne VSV particles from the site of infection to dLN." (PMID 30930901, 2019). "We hypothesized that macrophage polarization may have been impacted by the presence of Tlr7 and measured Arginase 1 (Arg1), a marker of macrophage phenotype, finding that expression was significantly increased upon infection in Tlr7-deficient BMMs." (PMID 29616197, 2018). "To define whether the protective effect of Tlr7-deficiency on S. Typhimurium infection was a function of the route of infection, we next infected the mice with S. Typhimurium via the intraperitoneal (i.p.)route." (PMID 29616197, 2018). "Furthermore, both qPCR and RNA-seq read analysis of longitudinal infection (4–20 hpi) show that TLR7, which also encodes a receptor important for recognition of ssRNA, had modest downregulation (approximately threefold) as infection progressed." (PMID 28848558, 2017). "Mice with TLR7 knocked out have been shown to be more susceptible to infection by JEV92." (PMID 29333229, 2016). "Indeed Tlr9−/− and Tlr7−/− mice were shown to be more susceptible than WT mice to infection with the parasite." (PMID 22496959, 2012). "X chromosome inactivation escape results in increased expression of TLR-7 in various immune cells, including B cells, which has been associated with higher antibody production among female mice in response to influenza A vaccination and infection using a murine model." (PMID 40438096, 2025). "In the studies of large yellow croaker, Japanese meagre and black rockfish, TLR7 showed a similar regulation tendency with SmaTLR7 in the head kidney or spleen after poly(I:C) infection, implying that the virus analogues could also cause the immune response of fish TLR7." (PMID 36232658, 2022). "Additionally, the results of western blot test further demonstrated that LEP and DPEP significantly inhibited the high protein expression of TLR4, TLR7, MyD88 and NF-κB p65 caused by influenza A virus infection, and the inhibitory effect was more obvious on the 3rd day of infection." (PMID 31551774, 2019). "In this study, we propose that the enhanced capacity of the innate immune system to clear virus during the acute infection phase has a profound impact on the disease pathogenesis including weight loss, lung inflammation and lung function and is attributed to the specific activation of TLR7." (PMID 30787331, 2019). "It would be interesting to examine whether TLR7 is implicated in sensing EV-A71 infection in pDCs." (PMID 30563052, 2018). "Microglia quickly detect viral pathogen-associated molecular patterns (PAMPs) through PRRs, such as TLR3 and TLR7, responding within minutes of infection." (PMID 41503211, 2026).
infection (continued). "We report a novel P435S gain-of-function (GOF) variant in TLR7 identified in a female patient presenting with early-onset SLE, recurrent infection, and neuroinflammatory features." (PMID 41846847, 2026). "We observed a significant increase in MA-CoV-2 titers on days 2 and 5 post-infection and in subgenomic RNA levels on day 2 post-infection in the lungs of TLR7−/− mice compared with those of infected control mice." (PMID 40162785, 2025). "In lung tissue, IL1B, IL6, IL10, CXCL2, CCL3 and CCL5 levels also rose in both genotypes following infection, although these markers were significantly lower in TLR7 KO mice." (PMID 40442368, 2025). "This is consistent with TLR7-mediated hyperinflammation worsening disease outcomes following infection with other ssRNA viruses." (PMID 40143355, 2025). "While lung expression of TLR3, DDX58 and NLRP3 remained unchanged in WT mice following infection, it was significantly higher in TLR7 KO mice." (PMID 40442368, 2025). "An in vitro infection of murine BMDMs isolated from TLR2-, TLR3- TLR4-, TLR7-, TLR9-, TLR2/TLR4-, and TLR2/TLR4/TLR9- deficient mice and cultured with Mtb showed that TLR9 was critical for protection against infection via FLT-3 ligand-generated DCs." (PMID 41236793, 2025). "TLR7 and IFITM3 are both endosomal proteins that have opposing effects on hMPV infection, with TLR7 promoting infection and IFITM3 restricting it." (PMID 40235933, 2025). "Following infection, macrophages of both sexes showed similar increases in TLR7 and IFNB expression, while significant upregulation of IL6 and TNFA was evident only in male macrophages." (PMID 40143355, 2025). "Further examination of protein levels of inflammatory cytokines (TNF and IL-1β) and chemokines (MCP-1) at day 2 post-infection showed significantly reduced levels of these mediators in TLR7−/− lungs compared to control lungs." (PMID 40162785, 2025). "This reduction infection was associated with decreased mRNA expression of TLR3 and TLR7, along with increased expression of antiviral genes, including PKR and OAS1." (PMID 40839599, 2025). "Our results showed significantly reduced CD69 levels in monocyte–macrophages and neutrophils of TLR7−/− lungs compared to control mice at day 2 post-infection." (PMID 40162785, 2025). "In the nasal tissue, the expression of endosomal TLRs, cytosolic RLRs and NLRP3 increased with infection in both genotypes, but levels (with the exception of TLR7) were higher in TLR7 KO mice." (PMID 40442368, 2025). "Lastly, immune stimulation through the use of Toll Like Receptor 7 (TLR7) agonists has demonstrated to be an effective tool to activate the innate immune response in bovine livestock, providing early protection against infection by A. marginale." (PMID 40438413, 2025). "Next, we examined the effects of TLR7 deficiency on lung virus titers and viral RNA levels in MA-CoV-2-infected control and TLR7−/− mice at days 2 and 5 post-infection." (PMID 40162785, 2025). "We found that in pDCs SLAMF7 and SLAMF8 are coregulated at the protein and mRNA levels in steady state and upon infection or TLR7/8 stimulation." (PMID 40231463, 2025). "After infection has been established, intracellular viral RNA can be recognized by the endosomal TLR7 and 8, or TLR3, which sense ssRNA or dsRNA, respectively." (PMID 39963132, 2025). "Remarkably, TASLDKO phenocopied feeble in all assays performed, i.e. ex vivo TLR7/9-induced signalling and global transcriptional responses, in vivo TLR7/9 stimulation as well as infection and autoimmune models." (PMID 39856058, 2025). "Previous studies have shown that either activating TLR7 via IMQ prior to IAV infection or inhibiting it with IRS661 during established infection reduces LRT pathology." (PMID 40442368, 2025). "This statement stems from the fact that SARS-CoV-2 titer is significantly higher in TLR7−/− lungs at both days 2 and 5 post-infection, at which time adaptive immunity plays a minor role." (PMID 40162785, 2025).
infection (continued). "In this study, we gained new insights into the mechanisms driving sex differences in RSV pathophysiology by showing a role for TLR7 in influencing the immune responses to infection by this virus." (PMID 40143355, 2025). "Deletion of TLR7 reduced the overall lung inflammatory response to infection, airway inflammation, and antibody response in both male and female mice." (PMID 40143355, 2025). "While TLR7 drives antiviral and inflammatory responses to infection in both sexes, females tend to have stronger inflammatory and antibody responses." (PMID 40143355, 2025). "Upon infection in low ROS-producing Ncf190H mice, the virus releases ssRNA, triggering the interferon signaling pathway, possibly through activation of TLR7 and the STING pathway." (PMID 39939342, 2025). "During infection with encephalomyocarditis virus, platelet-TLR7 stimulation mediates formation of large platelet-neutrophil aggregates, both in mouse and human blood." (PMID 39736771, 2024). "In an experimental model of L major infection, it was also demonstrated that TLR7 is critical for efficient neutrophil microbicidal responses with ROS production and control of infection." (PMID 38912968, 2024). "Depletion of Bst2+ cells or administration of TLR7 antagonists decreased lung immunopathology and morbidity, suggesting that pDCs play a deleterious role in this infection model." (PMID 38777879, 2024). "All of this is consistent with previous reports showing that lincRNA-Cox2 is overexpressed in a MyD88-dependent manner in response to the activation of various TLRs such as TLR2, TLR4, TLR7/8, or in response to infection with Listeria monocytogenes." (PMID 38464511, 2024). "Increased plasmacytoid dendritic cell frequency and diminished responsiveness to Toll-like receptor 7/8 ligand were observed in both controlled and natural infection settings." (PMID 39013877, 2024). "Using a model of multicellular spheroids, it was demonstrated that infection with the SARS-CoV-2 virus causes activation of RNA-recognizing receptors TLR3 and TLR7/8." (PMID 39457048, 2024). "Another example is the pairwise cooperation of TLR8 with TLR7 or TLR9 within endosomal membranes to regulate the eukaryotic inflammatory response upon detection of viral nucleic acids produced during infection." (PMID 39131286, 2024). "The significance of TLR7 in establishing adaptive immunological memory following infection also needs consideration, as previously reported." (PMID 39769461, 2024). "In our study, we found that TLR7 was involved in the immunopathogenesis of infection with RABV, and the expression of CCL2, CXCL10 and IL-6 were significantly increased in the terminal stage of infection with RABV." (PMID 39273091, 2024). "In Lee and colleague’s IBV work in kidney cells, up-regulation of TLR7 has been recorded at 48 h following infection." (PMID 38675946, 2024). "Both M1 and M2 macrophage responses were blunted in TLR7 KO mice across acute infection timepoints, consistent with the cytokine gene expression in the lung." (PMID 37795093, 2023). "This is unexpected because of the known roles of TLR7 are in antiviral immunity and protection against infection-induced exacerbations in respiratory diseases." (PMID 37963864, 2023). "TLR7-/- mice displayed a lower level of the percentage of splenic CD45+ IFN-γ+ cells than wild-type mice after the infection, which was a consequence of reduced production of IFN-γ in splenic T cells." (PMID 37180169, 2023). "There were overall fewer inflammatory cells infiltrating the lung tissue of TLR7 KO mice compared to WT mice during acute infection." (PMID 37795093, 2023). "Parallelly, in the infection of Plasmodium chabaudi, TLR7 is the primary Myd88-dependent sensor at 24 hours post infection, promoting IFN-α and IFN-β production and a cytokine response (IL-10, TNF, IL-12, and IFN-γ)." (PMID 37180169, 2023).
infection (continued). "TLR6 (respectively) and TLR7 (respectively) were significantly overexpressed in infection-derived EVs compared to control-derived EVs, while TLR3 (respectively) was expressed but significantly unchanged within EVs." (PMID 36979955, 2023). "Infection boosted IL-1β, IL6 and NLRP3 levels in TLR7 expressing AMФ but these proinflammatory markers were suppressed upon TLR7 deficiency." (PMID 37795093, 2023). "Nevertheless, we did not observe any difference in bone marrow erythropoiesis response between wild-type and TLR7-/- mice following the infection." (PMID 37180169, 2023). "Conversely, we found that expression of mucin genes was lower in TLR7 KO mice implying excess mucus secretion in response to infection occurred in the presence of TLR7." (PMID 37795093, 2023). "When monocytes were infected with ncp BVDV, the mRNA levels of TLR3, type I IFN and IL-12 were significantly increased at 1 h post infection, whereas the TLR7 mRNA was significantly upregulated in monocytes infected with both biotypes at 24 h post infection." (PMID 37900320, 2023). "When TLR7 gene was knockout, the percentage of pulmonary MDSCs was increased after infection and the expression of PD-L1/2 and IL-10 were increased in S. japonicum infection-induced pulmonary MDSCs." (PMID 36279265, 2022). "Expression of ICAM-1, a ligand for the integrin LFA-1, was significantly upregulated in both WT and Tlr7−/y after infection, but the magnitude of upregulation remained substantially greater in WT mice (factor of ~3)." (PMID 36278864, 2022). "Other recent studies show that modulation of immune responses using the TLR7 agonist imiquimod can reduce chronic infection and suppress subsequent infection by treated bradyzoites in an immunocompetent mouse model." (PMID 35075105, 2022). "Then, the expression of TLR7 was detected in isolated pulmonary MDSCs and the results showed that the expression of TLR7 in MDSCs was increased after infection." (PMID 36279265, 2022). "The expression levels ofTLR3 and TLR7 were observed in CEF NDV-challenged cells treated with various doses ofsialidase 48 h after infection." (PMID 35891661, 2022). "Lastly, expression of VCAM-1, ligand for the integrin VLA-4, was significantly reduced in both WT and Tlr7−/y during the infection, but to a lesser extent in Tlr7−/y mice." (PMID 36278864, 2022). "Vaccinated Arctic Charr showed significant expression of TLR7 after infection with Aeromonas salmonicida, activating B cells and DC to produce IFN-α and triggering Th1 and CD8+ T cell responses to demonstrate the effect of vaccination." (PMID 36439120, 2022). "Infection with S. aureus, or TLR7/8 signaling downstream of stimulation with antigen/antibody complexes resulted in activation of the ER stress sensor IRE1-α which was required for subsequent MitROS production." (PMID 36374941, 2022). "We interpret this data by assuming that the observed upregulation of TLR7 and downregulation of miR-146 occur after infection in these patients because a strong early TLR7-mediated IFN response would have protected them from the development of severe disease." (PMID 35065665, 2022). "Turning to the second question – and assuming that resensitization of the TLR7-signaling pathway does occur sometime after infection - why is the systemic response skewed, with an IFN response missing in the blood plasma ?" (PMID 35065665, 2022). "Here, our data showed that the percentage and numbers of MDSCs increased in the lung of infected mice, and the expression of TLR7 in pulmonary MDSCs was increased after infection." (PMID 36279265, 2022). "One the one hand, this „desensitization/resensitization“ model predicted a particular role of TLR7 for determining sensitivity to infection with SARS-CoV-2." (PMID 35065665, 2022).